CAT (catalase)
Diseases named in the same sentence as CAT in open-access papers (continued):
Sharing a sentence is not in itself a finding about the gene and the disease.
hydronephrosis (1 paper, 2015). Collection of urine in the renal pelvis that results in dilatation of the renal pelvis and calyces. "In our study, decreased Mn-SOD, GR, CAT levels and increased MDA, H2O2 levels were observed in rabbits with mild hydronephrosis subjected to 100 mmHg perfusion pressure and in rabbits with severe hydronephrosis subjected to 60 and 100 mmHg perfusion pressure." (PMID 26090815, 2015). "In rabbits with mild hydronephrosis, Mn-SOD, GR and CAT levels decreased when the perfusion pressure increased to 100 mmHg (p<0.05), however, the MDA and H2O2 levels increased in this group when subjected to a perfusion pressure of 100 mmHg (p<0.05)." (PMID 26090815, 2015). "In rabbits with severe hydronephrosis, the Mn-SOD, GR and CAT levels decreased when subjected to perfusion pressure of 60 mmHg or 100 mmHg (p<0.05); however, the MDA and H2O2 levels in this group increased when subjected to perfusion pressure of 60 mmHg or 100 mmHg (p<0.05)." (PMID 26090815, 2015). "Mn-SOD, GR, CAT, MDA and H2O2 levels levels in the rabbits with mild hydronephrosis perfused with fluid at pressures of 0 mmHg, 20 mmHg and 60 mmHg were also comparable, They were also comparable in rabbits with severe hydronephrosis perfused with fluid at pressures of 0 mmHg and 20 mmHg (p>0.05)." (PMID 26090815, 2015).
Hyperkeratosis (1 paper, 2006). Hyperkeratosis is a histopathological term defining a thickened stratum corneum and may be present in many different skin conditions, with many possible overlaps. "Both As and smoking are potent inducers of oxidative stress, and a recent small-scale study suggested that genetic susceptibility to oxidative stress, as determined by polymorphisms in the myeloperoxidase and catalase genes, is associated with elevated risk of developing As-related hyperkeratosis." (PMID 17185274, 2006).
hypertrophic cardiomyopathy (1 paper, 2020). A condition in which the myocardium is hypertrophied without an obvious cause. "Activities of superoxide dismutase and catalase differed in cats with hypertrophic cardiomyopathy, however the activity of the latter was only significantly lower in asymptomatic stage of the disease." (PMID 32000761, 2020). "In conclusion, the results indicate that the activities of superoxide dismutase and catalase are different in cats with hypertrophic cardiomyopathy, however the activity of the latter was only lower in asymptomatic stage of the disease." (PMID 32000761, 2020).
Hypoalbuminemia (1 paper, 2026). The concentration of albumin in the blood circulation is below the lower limit of normal. "IMID exposure resulted in significant hepatocellular and neuronal damage characterized by elevated serum ALT and AST, hypoalbuminemia, hypoproteinemia, increased MDA, suppression of SOD and CAT activities, and upregulated mRNA expression of TNF-α, IL-6, and HMGB1." (PMID 41838129, 2026).
hypochromic anemia (1 paper, 2023). Anemia caused by the reduction of hemoglobin in relation to the red cell volume. "It inactivates δ-ALAD and ferrochelatase (thus inhibiting heme biosynthesis and causing hypochromic anemia), and reduces the activity of the most important antioxidant enzymes: superoxide dismutase (SOD), catalase (CAT), and glutathione peroxidase (GPX)." (PMID 37048229, 2023).
Hypomagnesemia (1 paper, 2023). An abnormally decreased magnesium concentration in the blood. "Hypomagnesemia is commonly observed in HF and is associated with oxidative stress and suppressing the antioxidant defense system (e.g., SOD, CAT, GSH)." (PMID 38028798, 2023).
inflammatory skin disease (1 paper, 2024). Inflammatory skin disorders covers a broad category that includes many conditions ranging in severity, from mild itching to grave medical health complications These disorders are common in people of all ages and races. "Other authors also showed lower values of CAT and SOD in psoriatic patients compared to the other forms of inflammatory skin diseases." (PMID 38540199, 2024).
insulinoma (1 paper, 2016). "Next, to characterize intracellular and mitochondrial conditions according to antioxidant and prooxidant proteins, we examined how 2-DG and/or melatonin affected superoxide dismutase (SOD), catalase, Bcl-2, and Bax proteins in rat insulinoma INS-1E cells." (PMID 27493704, 2016). "We showed that 2-DG and/or melatonin affected SOD, catalase, Bcl-2, and Bax proteins in rat insulinoma INS-1E cells, suggesting that 2-DG or 2-DG plus melatonin influences antioxidant and prooxidant proteins through a mechanism involving mitochondrial ROS." (PMID 27493704, 2016).
interstitial cystitis (1 paper, 2023). A rare chronic debilitating urogenital disease characterized by urinary frequency, urgency, and pelvic pain. "At all experimental concentrations, it ameliorated interstitial cystitis symptoms by reducing bladder weight, vascular permeability, and expression levels of IL-6, TNF-α, TGF 1-β, and iNOS, while increasing SOD, CAT, and GSH levels." (PMID 37375759, 2023). "It produced a protective response in CYP-induced interstitial cystitis by improving levels of SOD and CAT." (PMID 37375759, 2023).
intoxication (1 paper, 2023). Disturbances in psychophysiological functions and responses as a result of administration or ingestion of a psychoactive substance. "Modulatory effect of CEBP on the activity of liver’s endogenous antioxidant enzyme system, namely CAT and SOD, in PCM-induced liver intoxication in rats." (PMID 37559390, 2023).
invasive breast carcinoma (1 paper, 2011). A carcinoma that infiltrates the breast parenchyma. "From a clinical perspective, mitochondrial targeted catalase should be considered as a potential adjuvant treatment strategy for further investigation to help prevent metastasis in women diagnosed with invasive breast cancer." (PMID 21605372, 2011). "We report in this paper that transgenic expression of mitochondrial targeted catalase in a clinically relevant mouse model of invasive breast cancer decreases primary tumor invasiveness and metastatic tumor severity." (PMID 21605372, 2011).
kidney cancer (1 paper, 2021). Primary or metastatic malignant neoplasm involving the kidney. "Therefore, we used ten fresh kidney cancer tissues to perform real-time fluorescent quantitative PCR experiments to detect the correlation between SOD2, CAT, and the macrophage marker CD68." (PMID 34721758, 2021).
kidney stones (1 paper, 2023). "In addition, CAT is a key target of BSHS anti-kidney stones according to 2.4.3, which protects cells from oxidative stress by scavenging hydrogen peroxide produced by cellular metabolism." (PMID 36864834, 2023).
lactic acidosis (1 paper, 2025). Metabolic acidosis characterized by the accumulation of lactate in the body. "Linezolid treatment resulted in lactic acidosis, increased serum levels of AST, ALT, urea, creatinine, and albumin, and oxidative stress characterized by decreased catalase activity and reduced glutathione (GSH) associated with increased nitric oxide (NO) malondialdehyde (MDA)." (PMID 40529491, 2025).
left ventricular hypertrophy (1 paper, 2025). Enlargement of the LEFT VENTRICLE of the heart. "In mice with left ventricular hypertrophy, preserved ejection fraction, diastolic dysfunction, and pulmonary congestion, resveratrol significantly reduced the release of IL-1β, IL-6, and TNF-α, as well as catalase (CAT), superoxide dismutase (SOD), and glutathione (GSH) activities." (PMID 41282017, 2025).
Leigh syndrome (1 paper, 2022). A progressive neurological disease defined by specific neuropathological features associating brainstem and basal ganglia lesions. "As a proof of the crucial role of CAT in metabolism, missense variants of CAT have been linked to Leigh syndrome." (PMID 35727434, 2022).
leiomyoma (1 paper, 2024). A well-circumscribed benign smooth muscle neoplasm characterized by the presence of spindle cells with cigar-shaped nuclei, interlacing fascicles, and a whorled pattern. "Leiomyoma cells exhibit lower expression of antioxidant enzymes, such as superoxide dismutase (SOD) and catalase (CAT), compared to normal uterine muscle cells, particularly in hypoxic environments." (PMID 39640883, 2024).
liposarcoma (1 paper, 2008). A usually painless malignant tumor that arises from adipose tissue. "When U2OS cells were co-transfected with the reported vector along with the FUS-DDIT3 expression vector, there was a specific increae of the CAT activity compared to the activity with the empty vector, demonstrating that FUS-DDIT3 is involved in the upregulation of eIF4E in liposarcomas." (PMID 18596980, 2008).
listeriosis (1 paper, 2022). A bacterial infection caused by Listeria monocytogenes. "Interestingly, several cases of human listeriosis have been attributed to catalase-negative L. monocytogenes strains (40, –, 43), which supports a need to reduce the reliance on the catalase test for identification of Listeria spp." (PMID 35658601, 2022).
lobular breast cancer (1 paper, 2022). "In addition, in lobular breast cancer, a decrease in catalase activity and uric acid concentration was more pronounced, while, in ductal breast cancer, the changes concerned AOA and salivary peroxidase activity." (PMID 35208240, 2022).
lung squamous cell cancer (1 paper, 2023). "CAT, ENO1, NQO1, P4HB, and PDIA6 were unique to LUAD, while CAV1, GAPDH, GPX2, GPX3, and PDIA4 exhibited consistent trends in differential expression in both LUAD and lung squamous cell cancer, significant prognostic survival prediction (p<0.05), and excellent classification effectiveness." (PMID 37955007, 2023).
lymphedema (1 paper, 2021). Excess fluid collection in tissues, causing swelling. "Considering that hemoglobin may be easily influenced during venipuncture and that the focus of this study was to investigate the oxidative stress associated with lymphedema, we chose four other protein targets (CAT, PRDX2, CA1, and CA2) for further validation of their expression by ELISA." (PMID 33917571, 2021).
McArdle disease (1 paper, 2017). "The main findings of the present study were that patients with McArdle disease show evidence of increased oxidative stress (8-isoprostanes and protein carbonyls) and a compensatory up-regulation of antioxidant enzymes (MnSOD and CAT) in skeletal muscle." (PMID 28649515, 2017).
memory (1 paper, 2020). The activities involved in the mental information processing system that receives (registers), modifies, stores, and retrieves informational stimuli. "The extract showed a significant improvement of memory impairment in Y-maze, in addition to a significant augmentation of the assessed antioxidant enzymes (SOD, GPx, and CAT), along with reduced levels of lipid peroxidation in the rat's whole brain homogenates." (PMID 33299461, 2020).
microcytic anemia (1 paper, 2015). Anemia in which the red blood cell volume is decreased. "Previous studies on the catalase activity of hypochromic microcytic anemia such as IDA and BTT have reported disagreeing results." (PMID 26527217, 2015). "Therefore, OxS is present in the most common hypochromic microcytic anemia, IDA and BTT, being one of the determining factors of altered catalase activity." (PMID 26527217, 2015).
Middle ear inflammation (1 paper, 2024). "Middle ear inflammation increases the levels of free oxygen radicals in erythrocytes, with the damage caused by these free radicals being mitigated by antioxidant enzymes such as CAT, GSH-Px, and SOD." (PMID 39857337, 2024). "Notably, CAT levels were low during the acute phase of otitis media, but increased as the condition progressed to the chronic phase." (PMID 39857337, 2024).
monocytic leukemia (1 paper, 2022). "The superoxide dismutase and catalase activities exhibited by PtNPs have also been shown in studies to further potentiate its interventional effect in aging-related skin, skeletal muscle, vascular endothelium, and monocytic leukemia in vitro models." (PMID 35624849, 2022).
mood disorder (1 paper, 2021). A cognitive disorder a disturbance in which the person's mood is hypothesized to be the main underlying feature. "Since oxidative damage is the result of the balance between oxidative products and the antioxidant defense, some studies in mood disorders have investigated this system, including superoxide dismutase (SOD), catalase, glutathione S-transferase (GST), and glutathione peroxidase (GPx)." (PMID 34295268, 2021).
morbid obesity (1 paper, 2024). An excess of body weight, normally defined as an individual with a body mass index greater than 35 or a body weight greater than one hundred percent of ideal body weight. "Decreased levels of CAT were found in patients with morbid obesity after bariatric surgery." (PMID 38703299, 2024). "Moreover, a significant decrease in abundance of CAT was found in patients with morbid obesity comparing to lean controls, additionally pointing to decrease in lipolysis within the mature adipocytes of SAT of this population." (PMID 38703299, 2024).
mucinous adenocarcinoma (1 paper, 2020). An invasive adenocarcinoma composed of malignant glandular cells which contain intracytoplasmic mucin. "Simultaneously, we observed significantly higher CAT activity in patients with adenocarcinoma than in subjects suffering from mucinous adenocarcinoma." (PMID 32575703, 2020).
mycotoxicosis (1 paper, 2021). Poisoning caused by the ingestion of mycotoxins (toxins of fungal origin). "The antioxidant enzymes, SOD and CAT showed a decline in the mycotoxicosis induced groups." (PMID 34593834, 2021).
necrotizing ulcerative gingivitis (1 paper, 2021). A bacterial infectious process affecting the gums. "This work shows the changes of malonic dialdehyde concentration as an indicator of lipid peroxidation intensity in experimental animals, the level of catalase activity in the blood of animals, and antioxidant-prooxidant balance in the dynamics of necrotizing ulcerative gingivitis." (PMID 33767788, 2021).
neonatal hepatitis (1 paper, 2010). "The three enzymes significantly increased in the extrahepatic biliary atresia group, whereas in the groups of neonatal hepatitis and paucity of intrahepatic bile ducts, only GPx and CAT enzymes were significantly increased." (PMID 20339177, 2010). "The three enzymes were significantly increased in the extrahepatic biliary atresia group, whereas in the groups of neonatal hepatitis and paucity of intrahepatic bile ducts, only GPX and CAT enzymes were significantly increased." (PMID 20339177, 2010). "The patients were divided into three groups: extrahepatic biliary atresia (n=13), neonatal hepatitis (n=15) and paucity of intrahepatic bile ducts (n=6); GPx, SOD and CAT levels were measured in fresh liver tissue using ELISA." (PMID 20339177, 2010).
nephrotic syndrome (1 paper, 2011). A collection of symptoms that include severe edema, proteinuria, and hypoalbuminemia; it is indicative of renal dysfunction. "Lipid Peroxidation and GPx were significantly higher in the nephrotic syndrome patients than in the controls, while SOD and catalase were significantly lower than in patients than in the control subjects." (PMID 22046528, 2011).
nocardiosis (1 paper, 2024). Nocardiosis is a local (skin, lung, brain) or disseminated (whole body) acute, subacute, or chronic bacterial infection. "Nocardiosis is a disease caused by gram-positive, catalase-positive, rod-shaped bacteria that stain weakly on a Gram stain." (PMID 38770507, 2024).
nodular sclerosis (1 paper, 2018). "In the glomeruli of patients with advanced DN, there was moderate to strong staining for Prx1, Prx2, GPx1, and catalase in the podocytes, particularly in the glomeruli having the lesions of nodular sclerosis (Kimmelstiel–Wilson lesion)." (PMID 30132841, 2018).
nosocomial infection (1 paper, 2022). An infection acquired in a hospital or other healthcare setting. "As opposed to E. coli, S. aureus is a Gram-positive opportunistic bacterium, catalase-positive, being considered a principal cause of nosocomial infections." (PMID 36297486, 2022).
obstructive sleep apnea (1 paper, 2020). "Previous studies have shown that there are transcript level variations in many genes involved in the regulation of reactive oxygen species (ROS), including heme oxygenase, superoxide dismutase, and catalase, in patients with obstructive sleep apnea." (PMID 33114225, 2020). "Further, microarrays have shown that there are transcript level variations in many genes involved in the regulation of reactive oxygen species (ROS), including heme oxygenase, superoxide dismutase, and catalase in patients with obstructive sleep apnea." (PMID 33114225, 2020).
opioid use disorder (1 paper, 2018). A substance-related disorder that involves the recurring use of opioids despite negative consequences. "We analyzed catalase (CAT), glutathione (GSH), malondialdehyde (MDA), superoxide dismutase (SOD) activity (as oxidative markers) and also MMP-9 and TNF-α level in the plasma of patients with opioid use disorder during two weeks of methadone therapy." (PMID 29892317, 2018). "We found an oxidative imbalance in patients with opioid use disorder before methadone therapy as demonstrated by lower SOD and catalase activity compared to the non-smoker comparison group." (PMID 29892317, 2018).
optic disc edema (1 paper, 2007). "Clearly, the additional benefit of ECSOD was not much greater than the solo effect of catalase that reduced optic disc edema by 32% with a mean optic nerve head area of 30,754 μm2 (Wt OD) relative to 45,354 μm2 for untreated eyes (Wt OS; p<0.01)." (PMID 17242675, 2007).
organophosphate poisoning (1 paper, 2025). Poisoning due to organophosphates (a class of organophosphorus compounds also known as phosphate esters, or OPEs). "Organophosphate poisoning among agricultural workers has been linked to reduced acetylcholinesterase activity and increased activities of SOD, CAT, and GPx." (PMID 41595828, 2025).
ovarian adenocarcinoma (1 paper, 2025). An adenocarcinoma that arises from the ovary. "Treatment with CUR alone significantly inhibited the growth of human ovarian adenocarcinoma SKOV-3/CDDP CDDP-resistant subline cells by inhibition the gene expression of the antioxidant enzymes (SOD1, SOD2, GPX1, CAT, and HO1), transcription factor NFE2L2 and signaling pathway (PIK3CA/AKT1/MTOR)." (PMID 39859517, 2025).
pancreatic adenocarcinoma (1 paper, 2023). "Furthermore, the combination of Capecitabine (a prodrug that is converted to 5-FU by thymidine phosphorylase) and Celecoxib (a Cox-2 inhibitor) reduced the number of mice with pancreatic adenocarcinoma, which was associated with a recovery of SOD and CAT activity." (PMID 36776312, 2023).
parasite (1 paper, 2021). "In conclusion, the SOD value in coral decreased 24 h after parasite infection, which may have been caused by the rapid proliferation of P. lucinda after coral infection, while CAT decreased significantly 36 h after infection." (PMID 34827209, 2021).
paroxysmal AF (1 paper, 2025). "Our clinical trial verified that the expression of MDA increased, whereas SOD, CAT and GSH/GSSG ratio decreased in the serum of patients with paroxysmal AF compared with that in individuals with a normal sinus rhythm." (PMID 40771918, 2025).
periapical periodontitis (1 paper, 2023). Inflammation of the periapical tissue. "The liver of rats with periapical periodontitis, compared with the control group, had higher levels of vitamin C, Na+/K+ATPase, and catalase activity, which indicated that there were oxidative stress reactions and hepatocyte degeneration induced by periapical periodontitis in the liver tissue." (PMID 37958220, 2023).